IL6 (interleukin 6)
Diseases named in the same sentence as IL6 in open-access papers (continued):
Sharing a sentence is not in itself a finding about the gene and the disease.
renal fibrosis (continued). "During advanced disease, inhibitors of the IL-6 pathway, especially those targeting IL-6 trans-signaling, significantly inhibit the recruitment of M2 macrophages, CD4+ T cells in mouse kidneys, thereby alleviating renal fibrosis." (PMID 39749325, 2024). "There was an age-based increase in pro-fibrotic and pro-inflammatory markers (IL-6, TNF, TGF-β1, and SNAIL1) in KO male mice that presumably contributed to renal fibrosis and renal damage (glomerular and tubular)." (PMID 37064891, 2023). "In the kidney, Ang II leads to excessive production of reactive oxygen species (ROS), renal vasoconstriction, and the release of pro-inflammatory mediators (IL-6 and TGF-β) through the activation of NADPH oxidase (NOX), ultimately leading to renal fibrosis." (PMID 37446016, 2023). "Q-PCR indicated a significant reduction in the expression of renal fibrosis-related genes (fn-1, αSMA, Col1a1, Col3a1, Ctgf, fsp1, KIM) and inflammatory cytokines (Tgfα, Tgfβ, Il-1b, Il-4, Il-6, CD44, CD68) in the kidney of the acetate-treatment group." (PMID 36922584, 2023). "The expression of IL-6 demonstrated a similar tendency, suggesting that UUO-induced inflammatory response and renal fibrosis were alleviated with decreased serum and renal IS accumulation." (PMID 37511089, 2023). "The results show that SQYSF can effectively reduce renal fibrosis in CKD mice, significantly reduce the expression of inflammatory factors TNF-α, IL-1β and IL-6, and can significantly change the composition of the mouse intestinal flora." (PMID 35184655, 2022). "VHH-0031, which can reduce the release of IL-6, TNF-α and TGF-β, is supposed to suppress renal fibrosis induced by EndMT and EMT in diabetic kidneys so as to improve renal injury and inhibit inflammatory response." (PMID 34054555, 2021). "An ELISA assay was performed to confirm the expressions of the inflammatory cytokines IL-6 and TNF-α, in UUO-induced renal fibrosis." (PMID 33806080, 2021). "We found that treatment with BMSC-EVs reverse UUO-induced increase of inflammatory cytokines TNF-α, IL-6, and IL-1β and macrophage infiltration, indicating that EVs effectively protect against UUO-induced renal fibrosis by inhibiting the inflammatory response." (PMID 32586368, 2020). "Candidate genes expression involved in renal fibrosis (TGF-β1, collagen type I and III) and inflammation (TNFα, IL-1β, IL-6 and MCP-1) were also measured by real-time qPCR." (PMID 33396267, 2020). "IL-6 invades the adipose tissue and influences transforming growth factor – beta 1 (TGF-β1) receptor trafficking, leading to renal fibrosis." (PMID 29454330, 2018). "However, the role of IL-6 in the pathogenesis of renal fibrosis is unknown." (PMID 23272241, 2012). "Activated cells produce TGF‐β, IL‐6, and IL‐23, driving Th17 activation and promote the formation of myofibroblasts, while CCR2+PIRB‐ macrophages secrete PDGFB promoting fibroblast proliferation, leading to the exacerbation of renal fibrosis." (PMID 40995682, 2025). "Additionally, ADAM17 cleaves cell membrane IL‐6R, releasing soluble IL‐6R, which binds to IL‐6 forming complexes that act on gp130 protein on immune cell membranes, activating the intracellular JAK/STAT pathway to induce renal fibrosis." (PMID 40077919, 2025). "Tubular cells, when damaged during renal fibrosis, transition to a secretory phenotype and generate fibrogenic agents such as sonic hedgehog (Shh), Wnt ligands, and TGF-β, as well as IL-6, monocyte chemotactic protein-1, TNF-α, and other inflammatory cytokines." (PMID 38808357, 2024). "Tocilizumab is an emerging therapy for conditions mediated by IL-6, and tocilizumab mimotope has demonstrated the ability to alleviate renal fibrosis by inhibiting ferroptosis in the UUO model, presenting a potential alternative therapy for renal fibrosis." (PMID 39769044, 2024).
renal fibrosis (continued). "There was also a positive correlation between IL6 expression and the severity of renal fibrosis, which further showed a negative correlation between IL6 and kidney function." (PMID 37205111, 2023). "SQYSF significantly reduced the degree of renal fibrosis in CKD mice, and remarkably down-regulated the expressions of toll-like receptor 5 (TLR5), nuclear factor-kappaB (NF-κb), p65, tumor necrosis factor (TNF)-α, interleukin (IL)-1β and IL-6." (PMID 35184655, 2022). "Also, the levels of damage markers in renal fibrosis, including ED-1 α-SMA, IL-6, IL-1β, TNF-α, TGF-β, NF-κB mRNA, CCL-2, CCL-5, collagen I, FN, collagen IV, and PCNA are decreased." (PMID 36268508, 2022). "Studies on specific targeting of IL-6 trans-signaling by using the sgp130Fc protein show a potentially novel strategy of renal fibrosis treatment by suppressing STAT3 activation without systemic IL-6 inhibition." (PMID 33670423, 2021). "Furthermore, several studies have demonstrated the inhibitory effect of emodin on renal fibrosis by suppressing the NF-ƙB p65 protein expression or the levels of ROS, TNF-α, and interleukin-6." (PMID 35002735, 2021). "Previous studies have shown that IL-6 does not play an important role in the development of renal fibrosis." (PMID 33959133, 2021). "FMT did not prevent the expression of renal fibrosis-related genes (TGFβ1 Transforming Growth Factor beta 1) and inflammatory cytokines (IL-6, Interleukin 6 and TNFα, Tumor Necrosis Factor alpha) in the kidney." (PMID 33255454, 2020). "IL-6 was shown to enhance TGF-β1 signaling via modulation of TGF-β1 receptor trafficking, an effect that may enhance renal fibrosis." (PMID 24885946, 2014). "In summary, our results demonstrate that IL-6 signaling does not play a significant role in the recruitment of bone marrow-derived fibroblasts into the kidney and the development of renal fibrosis induced by obstructive injury." (PMID 23272241, 2012). "Our results indicate that interleukin 6 does not play a significant role in the recruitment of bone marrow-derived fibroblast precursors and the development of renal fibrosis." (PMID 23272241, 2012). "Fibrosis reduction: MSCs decrease the levels of profibrotic factors such as IL-6, IL-1β, TNF-α, TGF-β, α-SMA, collagen I, and collagen IV while increasing the levels of antifibrotic factors such as FGFs, HGF, and VEGF, all of which inhibits EMT and reduces renal fibrosis." (PMID 40093796, 2025). "Among them, AKT1 and IL‐6 are the core targets and key downstream factors of the PI3K/AKT inflammatory pathway, respectively, which suggests that the mechanism of action of Solid Formula to improve renal fibrosis may be related to the PI3K/AKT pathway." (PMID 41245191, 2025). "Combined with the results of our network pharmacology, that is, both AKT1 and IL‐6 have a good binding ability with various active ingredients of GBXZF, we speculated that GBXZF could reduce the inflammatory response and improve renal fibrosis by upregulating the PI3K/AKT signaling pathway." (PMID 41245191, 2025). "In addition, SMAD2 and SMAD3 knockout augmented the production of inflammatory factor (TNFα and IL-6), while SIRT2-mediated NLRP3 deacetylation protects against inflammation, indicating SIRT2 may be a more attractive target to improving renal fibrosis." (PMID 37777567, 2023). "Interleukin-6 trans-signaling may affect kidney fibrosis, and suppression of this trans-signaling may protect podocytes and present an innovative therapeutic target for DKD and renal fibrosis." (PMID 36230932, 2022). "Additionally, IL-6 and MCP-1 expressions in kidney is coincident with renal fibrosis." (PMID 33260558, 2020).
myocarditis (152 papers, 2009 to 2026). Myocarditis is a condition that is characterized by inflammation of the heart muscle (myocardium). "As a key mediator of the immune response, IL-6 is closely associated with various inflammatory diseases, including myocarditis." (PMID 41200189, 2025). "NLRP3 activation leads to the release of interleukin-1β (IL-1β), tumor necrosis factor-alpha (TNF-α), and interleukin-6 (IL-6), cytokines that are directly implicated in the pathogenesis of myocarditis and other cardiovascular inflammatory disorders." (PMID 40870916, 2025). "Inhibition of TRIM29-PERK signaling pathway can reverse the myocarditis caused by inflammatory cytokines such as IL-6, IL1-β and TNF-α." (PMID 38979420, 2024). "Patients with cardiac injury also demonstrate elevated IL-6 levels, with fulminant myocarditis attributed to a cytokine storm as a potential cause." (PMID 38448675, 2024). "Of note, IL-6 is also implicated in the pathophysiology of myocarditis and in recruiting inflammatory cells to the myocardium." (PMID 36851722, 2023). "IL-2 implicated in myocarditis, and IL-4, IL-6, and IL-13 implicated in fibrosis and cardiomyopathy are the other inflammatory interleukins suppressed by NP-6A4." (PMID 34220518, 2021). "In patients with myocarditis, increased amounts of IL-1β and IL-6 correlated with higher levels of pathogenic T helper 17 cells." (PMID 33881711, 2021). "Myocarditis is an inflammatory process secondary to inflammatory infiltration and myocardial damage.IL6 is a mediator of cytokine storm that cause T- lymphocyte activation and T- cell mediated cytotoxicity." (PMID 34630967, 2021). "Recent multiparametric approaches combining cytokines with necrosis markers—such as IL-6, troponins, and NT-proBNP—may enhance diagnostic reliability in myocarditis-related deaths." (PMID 41596321, 2026). "Given the enrichment of IVT mRNA in the cytoplasm, we hypothesized that it might function as a ceRNA to regulate IL-6 translation by sponging specific miRNAs implicated in the pathogenic process of myocarditis." (PMID 41200189, 2025). "There is growing evidence that suggests that males have a higher risk of outcomes in the case of myocarditis, despite the fact that they are able to suppress the production of pro-inflammatory cytokines (IL-1β, IL-6 and TNF-α) and increasing the production of anti-inflammatory cytokines." (PMID 37112659, 2023). "The increase in systemic levels of SDF-1, IL-1β and il-6 indicates systemic pro-inflammatory effects induced by ICIs that can directly and indirectly increase the risk of myocarditis, however more detailed studies on the mechanisms of systemic and direct cardiac toxicity will have to be carried out." (PMID 36158826, 2022). "We found that this combination induced a significant release of LDH (more than 30%) in co-cultures of cardiomyocytes and lymphocytes associated with significant secretion of pro-inflammatory IL-6, which has been previously reported to be involved in the etiopathogenesis of myocarditis." (PMID 34201082, 2021). "Consistently with the presence of myocardial inflammation, RT-qPCR analysis showed elevated mRNA levels of IL-1β and IL6 shortly after DEP exposure, with a similar trend for TNFα and the macrophage marker EMR1." (PMID 41444986, 2025). "The results show that the most common cytokines to be elevated in the peripheral blood during ICI myocarditis are IL-6 and TNF-α with a surprising minority of patients with IFN-γ elevation and none with IL-1β elevation." (PMID 38785743, 2024). "Quantitative RT–PCR analysis of sorted cardiac fibroblasts confirmed the increased expression of the inflammatory monocyte-attracting chemokine Ccl2 and the inflammatory cytokine Il6 during autoimmune T cell-driven myocarditis." (PMID 39196111, 2024). "This is due to the strong association between myocarditis and ACS with inflammatory cytokines, such as IL-1β and IL-6." (PMID 39452475, 2024).
myocarditis (continued). "In a transverse aortic constriction (TAC)-induced mouse heart failure model, inhibiting IL6/gp130/STAT3 with raloxifene alleviated TAC-induced myocarditis, cardiac remodeling and dysfunction." (PMID 38495094, 2024). "In our study, we showed that TNF-α and IL-6 are elevated in patients presenting with ICI myocarditis but have limited value in prognostication and guiding treatment." (PMID 38785743, 2024). "The other possibility involves the virus triggering immune response in the form of cytokine storm releasing IL-6, IL-10, and TNF-alpha, causing myocarditis." (PMID 36902636, 2023). "Cardiomyocytes and cardiac fibroblasts were identified as the main producers of IL-6 during myocarditis." (PMID 37175422, 2023). "TNF-α, IL-6, and IL-17 secretion by B cells promoted Th1 and Th17 differentiation during myocarditis, while the downregulation of IL-4 significantly limited Th2 differentiation." (PMID 37175422, 2023). "Activated NF-κB promotes the transcription and release of proinflammatory mediators such as interleukin-6 (IL-6) and tumor necrosis factor-α (TNF-α), which causes myocardial inflammation." (PMID 37747066, 2023). "We measured the levels of the proinflammatory cytokines IL-1β, IL-6, IL-8, and the regulatory cytokine IL-10 in myocarditis and control serum." (PMID 35265721, 2022). "There is consistency between the increased expression of costimulatory molecules in myocarditis DCs and the higher levels of IL-6 and IL-8 observed." (PMID 35265721, 2022). "It expands the infiltration and accumulation of CD4+ and CD8+ T cells in the myocardium and promotes the release of myocarditis factors (such as IL-2, IL-6, etc.)." (PMID 36186992, 2022). "A number of clinical trials revealed that elevated levels of TNF-α, IL-6, IL-8 and other pro-inflammatory cytokines participated in the pathogenesis of cardiac damage during myocarditis." (PMID 34465337, 2021). "Since myocarditis patients with comorbidities had counterintuitive lower levels of IL-6, this finding deserves to be further investigated to better understand myocarditis prognostic and pathogenetic factors and to evaluate a specific target therapy." (PMID 33663062, 2021). "One of the early reports describing myocardial inflammation in SARS‐CoV‐2 infection reported fulminant myocarditis with elevated IL‐6 levels along with other cardiac injury markers." (PMID 34765640, 2021). "Captopril decreased the concentration of IL-1 beta and IL-6 in the different inflammatory rat models of renal hypertension, hepatic injury, myocarditis as well as IL-8 reduction of human coronary artery endothelial cells." (PMID 34768805, 2021). "This case series of ICI-related myocarditis supports the use of anti-IL-6 therapy in CS-refractory myocarditis." (PMID 34686542, 2021). "IL6 is a key cytokine in mouse-induced T. cruzi myocarditis, triggering protection mechanisms in cardiomyocytes but favoring a higher parasite load." (PMID 33193300, 2020). "Serum levels of IL-6 and its mRNA and protein expression in cardiac tissues are significantly increased in patients with cardiac diseases, including heart failure, myocarditis, septic cardiomyopathy, myocardial infarction, and cardiac myxoma." (PMID 33071805, 2020). "In our study, two patients died of myocarditis after high doses of intravenous glucocorticoids and anti‐IL‐6 antibody." (PMID 32468726, 2020). "Serum levels of IL-6 are elevated in the mouse model of EAM and in patients with acute myocarditis, which is associated with a poor prognosis." (PMID 33643041, 2020). "On the other hand, STAT3 contributes to immune-mediated myocarditis due to IL-6-induced complement component C3 production in the liver, as well as the differentiation of Th17 cells, which play a role in initiation and development of myocarditis." (PMID 30619368, 2018).
myocarditis (continued). "Histopathology examination of mouse hearts showed that IL‐6KO mice receiving recombinant IL‐6 iv developed myocarditis comparable to WT mice, whereas IL6KO mice were resistant to EAM." (PMID 28474508, 2017). "Histopathologic examination of mice hearts demonstrated that mice immunized with IFA and treated with recombinant IL‐6 at the day 0 developed myocarditis." (PMID 28474508, 2017). "Meanwhile, marked increases in Treg cells and Treg-related cytokines (TGF-β, IL-10 and IL-6) also were observed in myocarditis mice." (PMID 27724948, 2016). "Innate immune cytokines such as TNF-α, IL-1β, and IL-6 are essential for the development of acute viral-induced myocarditis." (PMID 26507386, 2015). "Significant correlation of IL-6 and hsCRP with the mitochondrial chaperonic protein Hsp60 and pro-apoptotic Bax in sera, respectively, suggests that myocardial inflammation mostly affected the integrity of mitochondrial membranes." (PMID 25888309, 2015). "On day 7, the cardiac IL-1β, TNF-α, IL-6 and IL-17A levels were significantly downregulated in the group of 0.2 and 0.4 mg/kg nicotine compared to the myocarditis group." (PMID 26507386, 2015). "Elevated levels of serum IL-6 have been observed in myocarditis patients compared to healthy controls, and have been related to the degree of cardiac dysfunction and overall poor outcome." (PMID 25462010, 2014). "The Person correlation analysis showed that on day 7, the TNF-α and IL-6 levels in the myocarditis, nicotine and methyllycaconitine groups were negatively correlated with their corresponding p-STAT3 levels." (PMID 25396421, 2014). "Further, we demonstrate that STAT3 is sufficient when constitutively active for triggering the onset of immune-mediated myocarditis, involving enhanced complement C3 production and IL-6 signalling amplification in the liver." (PMID 23460527, 2013). "Further, we demonstrate that STAT3 is sufficient when constitutively active for triggering the onset of auto-immune myocarditis, involving enhanced complement C3 production and IL-6 signalling amplification in the liver." (PMID 23460527, 2013). "Patients with acute myocarditis displayed elevated circulating IL-6 and C Reactive Protein levels, which correlated with significantly higher circulating C3, compared to healthy controls or to samples from DCM or chronic myocarditis." (PMID 23460527, 2013). "This appears to be relevant to disease pathogenesis in humans, since acute myocarditis patients display significantly elevated circulating IL-6 and C3 levels and activated heart STAT3." (PMID 23460527, 2013). "Clinical studies have also found increased levels of circulating tumor necrosis factor-α (TNF-α), interleukin (IL)-1β, IL-6 and other pro-inflammatory cytokines in patients with myocarditis." (PMID 23029542, 2012). "MCP-1 stimulates an inflammatory response in cardiomyocytes by enhancing IL-6 levels and is involved in the pathogenesis of myocarditis." (PMID 22761780, 2012). "Variance in convalescent TNF-α levels was related to IL-6 variance but was not strongly associated with peak VO2 or with myocardial inflammation." (PMID 39969260, 2025). "The innate cell release of TNFα, IL-1β and IL-6 as well as complement activation are well documented in viral and autoimmune models of myocarditis, especially in males, where they increase acute and chronic myocarditis." (PMID 38464847, 2024). "In our cohort, both TNF-α and IL-6 were elevated during the presentation with ICI myocarditis." (PMID 38785743, 2024). "Serum IL-6 levels have been strongly correlated with cytokine storms and myocarditis." (PMID 39452475, 2024). "In addition, the authors, analyzing the inflammatory responses induced by the virus (as production of IL-1 or IL-6), postulated on the possible role of Interferon-ß or Anakinra for acute B19V-induced myocarditis." (PMID 39696462, 2024).